FH (fumarate hydratase)
Diseases named in the same sentence as FH in open-access papers (continued):
Sharing a sentence is not in itself a finding about the gene and the disease.
autosomal dominant disease (4 papers, 2021 to 2024). Autosomal dominant form of disease. "HLRCC is a rare, autosomal dominant hereditary disorder caused by mutations in the FH gene." (PMID 39160519, 2024).
benign tumor (4 papers, 2016 to 2025). "Multiple appearances of benign tumours histologically proved to be cutaneous leiomyomatosis suggest a rare disorder with germline heterozygous pathogen variant in the FH gene." (PMID 40264827, 2025).
cardiovascular disease (2 papers, 2023). "This study emphasizes the significance of genetic testing in identifying rare or novel FH mutations in underrepresented populations, which has the potential to reduce the burden of cardiovascular disease (CVD) in risk-group countries." (PMID 37469559, 2023).
mitochondrial disease (2 papers, 2017 to 2019). "Fumarate deficiency is a mitochondrial disease resulting from a defect in the fumarate hydratase gene (ENSG00000091483) that encodes both cytosolic and mitochondrial isoforms, and that converts fumarate to malate—a key step in the TCA cycle." (PMID 29178872, 2017).
neurodegenerative disease (1 paper, 2022). A disorder of the central nervous system characterized by gradual and progressive loss of neural tissue and neurologic function.
FH also shares sentences with these, for which no sentence is quoted: bladder cancer (6 papers); leiomyomatosis (6); gastrointestinal stromal tumor (5); glioblastoma (5); neuroblastoma (4); oncocytoma (4); ovarian carcinoma (4); triple-negative breast carcinoma (3); Arthritis (2); brain malformations (2); breast adenocarcinoma (2); cardiac disease (2); chromophobe renal cell carcinoma (2); developmental delay (2); Familial adenomatous polyposis (2); head and neck paraganglioma (2); hereditary papillary renal carcinoma (2); hereditary renal cell carcinoma (2); ischemic stroke (2); mesothelioma (2); prostate adenocarcinoma (2); renal fibrosis (2); renal oncocytoma (2); urothelial carcinoma (2); acute porphyria (1); adenoma (1); adenomyosis (1); adrenocortical adenoma (1); adrenocortical carcinoma (1); Alport syndrome (1).
A further 95 diseases each share a sentence with FH in 1 paper.